SH3GL2 (SH3 domain containing GRB2 like 2, endophilin A1)
Diseases named in the same sentence as SH3GL2 in open-access papers (continued):
Sharing a sentence is not in itself a finding about the gene and the disease.
ischemia (1 paper, 2021). A hypoperfusion of the BLOOD through an organ or tissue caused by a PATHOLOGIC CONSTRICTION or obstruction of its BLOOD VESSELS, or an absence of BLOOD CIRCULATION. "The neuroprotective effect of Control-SH3GL2 and Tat-SH3GL2 against ischemic damage was evaluated by analyzing the spontaneous motor activity of the animals one day after ischemia as hyperactivity was known to be induced by ischemic damage in the hippocampus." (PMID 33572372, 2021). "PSD95, synaptophysin, and SNAP-25 levels were assessed in the hippocampus by Western blot analysis because ischemia and Tat-SH3GL2 have been shown to affect synaptic plasticity in the hippocampus." (PMID 33572372, 2021). "In the Tat-SH3GL2-treated group, however, PSD95, synaptophysin, and SNAP-25 levels were significantly higher in the hippocampus at 1 day and 4 days after ischemia compared to those in the Tat peptide or Control-SH3GL2-treated groups." (PMID 33572372, 2021). "In the present study, we analyzed the levels of TNF-α, IL-1β, and IL-6 in the hippocampus to validate the roles of Tat-SH3GL2 on ischemia-induced inflammatory responses because TNF-α promotes the migration of neurotrophils, IL-1β, and IL-6, which show pro-inflammatory roles." (PMID 33572372, 2021). "Treatment with Tat peptide or Control-SH3GL2 significantly increased the travel distance by more than 2.5-fold compared to that in the control group, and Tat-SH3GL2 treatment significantly ameliorated the increase in travel distance 1 day after ischemia." (PMID 33572372, 2021). "In the Tat peptide- and Control-SH3GL2-treated groups, PSD95 protein levels gradually decreased 1 day and 4 days after ischemia, while synaptophysin and SNAP-25 levels increased 4 days after ischemia." (PMID 33572372, 2021). "In the Tat peptide- and Control-SH3GL2-treated groups, MDA levels were significantly elevated 3 h after ischemia and decreased 12 h post ischemia, although MDA levels were significantly higher than that of their respective controls." (PMID 33572372, 2021). "To identify the possible mechanisms of Tat-SH3GL2 against ischemic damage, we observed MDA and 8-iso-PGF2α levels in the hippocampus at different times after ischemia induction because MDA and 8-iso-PGF2α are reliable markers of lipid peroxidation." (PMID 33572372, 2021). "SH3GL2 immunoreactivity was decreased in the gerbil hippocampal CA1 region with time after ischemia, but it was maintained in the other regions after ischemia." (PMID 33572372, 2021). "Neuroprotective mechanisms of Tat-SH3GL2 and Control-SH3GL2 were evaluated by ELISA for MDA and 8-iso-PGF2α in the hippocampus at early time points after ischemia induction." (PMID 33572372, 2021). "In the present study, we observed ischemia-dependent decreases of SH3GL2 immunoreactivity in the hippocampal CA1 region, but not in CA3 and the dentate gyrus in gerbils." (PMID 33572372, 2021).
leukemia (1 paper, 2017). A malignant (clonal) hematologic disorder, involving hematopoietic stem cells and characterized by the presence of primitive or atypical myeloid or lymphoid cells in the bone marrow and the blood. "Furthermore, the circRNA-miRNA-mRNA interaction network of hsa_circ_0004277 from cytoscape analysis offered us several downstream gene-candidates, among which SH3GL2 and PPARGC1A were reported to be involved in several solid tumors, and SH2B3 especially as “a new leukemia predisposition gene”." (PMID 28282919, 2017).
pancreatic adenocarcinoma (1 paper, 2022). "Apart from GBM, SH3GL2 deviation was marked in the kidney chromophobe tumor (KICH), kidney renal cell carcinoma (KIRC), pancreatic adenocarcinoma (PAAD), prostate adenocarcinoma (PRAD), and sarcoma (SARC)." (PMID 35571016, 2022).
retinal degeneration (1 paper, 2017). Degeneration of the retina. "They include genes involved in nuclear trafficking and gene silencing (IPO8), fast axonal guidance and synaptic specificity (PCDH12), transduction of nerve signals (NRSN1), retinal degeneration (LMO7), synaptic glutamate release (SH3GL2), and broader nervous system development and function." (PMID 29064472, 2017).
triple-negative breast carcinoma (1 paper, 2022). An invasive breast carcinoma which is negative for expression of estrogen receptor (ER), progesterone receptor (PR), and human epidermal growth factor receptor 2 (HER2). "In triple negative breast cancers, SPANXB1 expression has been identified in circulating small extracellular vesicles and is thought to be acted upon by metastasis suppressor SH3GL2." (PMID 35614362, 2022).
tumor (17 papers, 2013 to 2025). "Thus, SPANXB1 loss with rescued SH3GL2 expression in SPANXB1-KD cells not only prevents primary tumor growth but also their progression to metastasis." (PMID 31406142, 2019). "Moreover, SH3GL2 dysregulation has been associated with increased blood–brain barrier permeability, which may promote tumor progression." (PMID 36408514, 2022). "Several mechanisms have been reported to decrease SH3GL2 expression in tumor cells, including chromosomal deletion, promoter hypermethylation, microRNA upregulation, and single nucleotide polymorphisms affecting transcript stability." (PMID 40986063, 2025). "An increased expression ratio of SH3GL2:SPANXB1 was evident in the primary tumor tissues obtained from the SPANXB1-KD mice." (PMID 31406142, 2019). "The SH3 domain containing GRB2-like 2, endophilin A1 (SH3GL2, also known as endophilin-1) is a potential tumor suppressor gene that is highly expressed in the brain, particularly in presynaptic ganglion." (PMID 30577490, 2018). "The similar case is SH3GL2, deletion of which downregulates tumor growth by modulating EGFR signaling." (PMID 27610367, 2016). "SH3GL2 is mainly distributed in the central nervous system and considered to be a tumor suppressor in many tumors." (PMID 24736727, 2014). "Similarly, reduced SH3GL2 expression in retinoblastoma cells, particularly observed in invasive cells, augments migration and tumor growth and, by increasing the amount of myeloid-derived suppressor cells, promotes immunosuppression." (PMID 40986063, 2025). "Conversely, enhancing SH3GL2/1/3 gene expression may be beneficial in diseases where they exert protective effects, for example as tumor suppressor in some cancer types or in cardiovascular diseases." (PMID 40986063, 2025). "Thus it was evident that overall alterations (deletion/methylation) of SH3GL2 was high (63%, 19/30) in dysplastic lesions and became comparable (64%–77%) in subsequent stages of tumor progression." (PMID 23675485, 2013). "Our data suggests that overexpression of EGFR protein might be due to the impairment of the SH3GL2 associated endocytosis mechanism, whereas down regulation of CDC25A in this tumor might lead to the EGFR protein in its active state." (PMID 23675485, 2013). "Thus, in the absence of other discriminatory markers, overexpression of DDP10, ETNPPL and SH3GL2 in DA + AA vs GBM might be considered in distinguishing these tumor subgroups, particularly for unclassifiable tumors or in case of small biopsy samples." (PMID 32647207, 2020). "High expression of ARFIP2, SH3GL2, and SRGAP3 help maintain cell tension and stiffness as well as inhibit tumor invasion and metastasis." (PMID 36408514, 2022). "A statistically significant correlation was observed between SH3GL2 and CDC25A alterations (p = 0.05) in tumor samples." (PMID 23675485, 2013). "Many of the genes epigenetically silenced by upY-Stat5a carry tumor suppressive functions (e.g., TIMP4, SH3GL2), suggesting upY-Stat5a itself may be involved in hPRLrL+I-driven mammary transformation." (PMID 33772010, 2021). "These might include genes with tumor suppressive properties, such as CDKN2B (9p21), SH3GL2 (9p22), PTPRD (9p23), and DOCK8 (9p24)." (PMID 27835607, 2016). "Our results proved that SH3GL2 had a reduced expression level in the GSCs compared with non-GSCs, suggesting that SH3GL2 was a tumor suppressor in GSCs." (PMID 24736727, 2014). "We also found that while RRM2 and SH3GL2 were differentially expressed in GBM, their expression had no prognostic value for GBM, suggesting that they are tumor-specific, but not GBM specific." (PMID 27655637, 2016).
cancer (5 papers, 2010 to 2022). A tumor composed of atypical neoplastic, often pleomorphic cells that invade other tissues. "The hub genes identified by PPI network analysis include SYN1, CNTN2, FAIM2, MT3, and SH3GL2, which are involved in the pathogenesis of different cancers." (PMID 32328342, 2020). "It is a multifunctional gene, except for its endocytic functions, the non‐endocytic functions of SH3GL2 may play a crucial role in the malignant progression of cancer." (PMID 28470949, 2017). "Furthermore, pan-cancer analysis of the hub genes revealed three genes, namely, CACNA1E, DDN, and SH3GL2, which were predominantly downregulated in GBM but not identified in more than five cancer types, could also make them putative prognostic biomarkers for GBM." (PMID 35571016, 2022).
neurodegenerative disease (1 paper, 2023). A disorder of the central nervous system characterized by gradual and progressive loss of neural tissue and neurologic function. "The results showed that the single-cell samples of the CA1 subregion were mainly involved in vesicle-mediated transport in synapse and neurodegenerative disease-related functions, and Syn2, Sh3gl2, Aldoa, Tubb2a and Eno1 were screened as the key target genes." (PMID 36768134, 2023).
SH3GL2 also shares sentences with these, for which no sentence is quoted: Alzheimer disease (6 papers); Parkinson (2); schizophrenia (2); autism (1); bipolar disorder (1); brain cancer (1); brain tumors (1); depression (1); diabetes (1); diabetic kidney disease (1); glomerular diseases (1); large-cell neuroendocrine lung carcinoma (1); lung adenocarcinoma (1); lupus nephritis (1); medulloblastoma (1); membranous nephropathy (1); memory impairment (1); neuroblastoma (1); ovarian carcinoma (1); pituitary adenoma (1); prostate adenocarcinoma (1); sarcoma (1); temporal lobe epilepsy (1); tobacco use disorder (1).